CIC (capicua transcriptional repressor)
Diseases named in the same sentence as CIC in open-access papers (continued):
Sharing a sentence is not in itself a finding about the gene and the disease.
adult T-cell leukemia/lymphoma (1 paper, 2024). A peripheral (mature) T-cell neoplasm linked to the human T-cell leukemia virus type 1 (HTLV-1), adult T-cell leukemia/lymphoma is endemic in several regions of the world, in particular Japan, the Caribbean, and parts of Central Africa. "ATXN1 or CIC alterations are present in 53% of adult T-cell leukemia/lymphoma (ATLL) cases, and CCR4 (C–C chemokine receptor 4) mutations are common, and the majority of ATLL patients exhibit CCR4 overexpression, which is associated with skin involvement and worse prognosis." (PMID 38178117, 2024).
Alzheimer disease (1 paper, 2024). A progressive, neurodegenerative disease characterized by loss of function and death of nerve cells in several areas of the brain leading to loss of cognitive function such as memory and language.
anaplastic gliomas (1 paper, 2016). "In a different study, anaplastic gliomas were classified based on ATRX, CIC, FUBP1 and IDH status and patients with ATRX and IDH mutated tumors showed a significantly longer overall survival compared to patients with mutated IDH and wild type ATRX tumors." (PMID 27311324, 2016).
anaplastic oligodendroglioma (1 paper, 2013). A WHO grade III oligodendroglioma with focal or diffuse malignant morphologic features (prominent nuclear pleomorphism, mitoses, and increased cellularity). "Only twelve of these tumors actually have concomitant mutations in FUBP1 and CIC, and nine of these cases are anaplastic oligodendrogliomas." (PMID 23527265, 2013). "Based on aCGH data and limited analysis of exome sequencing, the tumor reported here has a common anaplastic oligodendroglioma genomic profile including FUBP1, CIC, and IDH1 mutations." (PMID 23527265, 2013).
astrocytic tumor (1 paper, 2015). A glial tumor of the brain or spinal cord showing astrocytic differentiation.
Autoimmunity (1 paper, 2021). The occurrence of an immune reaction against the organism's own cells or tissues. "Here, we show that Capicua (CIC), a transcriptional repressor that suppresses autoimmunity, controls the thymic selection process." (PMID 34895467, 2021).
brain cancer (1 paper, 2019). A primary or metastatic malignant neoplasm affecting the brain. "Genomic analyses of brain cancers have implicated CIC as a tumor suppressor gene in diffuse gliomas, particularly ODGs3,4,36." (PMID 31043608, 2019).
citrin deficiency (1 paper, 2023). "Another rare cause of elevated citrate levels is citrin deficiency, which is characterized by aspartate/glutamate carrier deficiency and upregulation of mitochondrial citrate/isocitrate carrier (CiC, also known as SLC25A1) leading to citrin deficiency." (PMID 37686138, 2023).
coronary artery disease (1 paper, 2014). "Other genes in this region include CIC, which is a transcriptional suppressor involved in early organ development, CNFN (involved in hematopoiesis), CXCL17 (involved in angiogenesis), and PAFAH1B3 (related to coronary artery disease and organ development)." (PMID 24555826, 2014).
dengue (1 paper, 2009). "Factor H was also highly correlated with platelet levels in the dengue patients, whereas C1q, CIC-C1q, CRP, and MBL protein levels were not." (PMID 19707565, 2009).
desmoplastic small round cell tumor (1 paper, 2025). Desmoplastic small round cell tumor (DSRCT) is an aggressive soft tissue cancer that typically arises in serous lined surfaces of the abdominal or pelvic peritoneum, and spreads to the omentum, lymph nodes and hematogenously disseminates especially to the liver. "However, despite its high sensitivity, CD99 is not entirely specific, as it is also expressed in a wide range of malignancies, including small round blue cell tumors like Ewing sarcoma, desmoplastic small round cell tumors (DSRCT), CIC-rearranged sarcomas, and BCOR-altered neoplasms." (PMID 40307756, 2025).
DiGeorge syndromes (1 paper, 2012). "The mitochondrial citrate transporter gene, SLC25A1 or CIC, maps on chromosome 22q11.21, a region amplified in some tumors and deleted in developmental disorders known as velo-cardio-facial- and DiGeorge syndromes." (PMID 23100451, 2012).
head and neck cancer (1 paper, 2014). A primary or metastatic malignant neoplasm affecting the head and neck. "Our analysis of the CBioPortal database for cancer genomics also demonstrated alterations in copy number as well as mutations of the CIC gene in various tumors, including lung, ovary, bladder and head and neck cancers." (PMID 24681808, 2014).
hepatocellular carcinoma (1 paper, 2022). A malignant tumor that arises from hepatocytes. "CIC mutations have subsequently been associated with advanced stage lung adenocarcinomas, metastatic progression of prostate cancer, gastric adenocarcinoma, and hepatocellular carcinoma." (PMID 36358827, 2022).
Hyperglycemia (1 paper, 2016). An increased concentration of glucose in the blood. "In liver from diabetic rats, correction of hyperglycemia with phlorizin restored CiC activity and protein level to values measured in control animals." (PMID 27231907, 2016). "However, the molecular mechanism/s by which hyperglycemia affects CiC expression is not so far understood." (PMID 27231907, 2016).
hypothyroidism (1 paper, 2017). Abnormally low levels of thyroid hormone. "It has been demonstrated that hypothyroidism negatively affects the CiC expression at both transcriptional and post-transcriptional levels, through the inhibition of transcriptional rate of CiC mRNA and of its splicing." (PMID 28362337, 2017).
lung adenocarcinoma (1 paper, 2025). A carcinoma that arises from the lung and is characterized by the presence of malignant glandular epithelial cells. "Here we identify the transcriptional repressor Capicua (CIC) as a key target inactivated by KRAS/MAPK signaling in lung adenocarcinoma." (PMID 41219537, 2025).
melanoma (1 paper, 2022). A malignant, usually aggressive tumor composed of atypical, neoplastic melanocytes. "In summary, our meta-analyses of 147 acral and 93 mucosal melanomas identified PTPRJ, FER, SKP2, LZTR1, CIC, and PRKN as part of a long tail of driver events that deserves further study and characterization." (PMID 35706047, 2022).
metabolic syndrome (1 paper, 2016). A cluster of metabolic risk factors for CARDIOVASCULAR DISEASES and TYPE 2 DIABETES MELLITUS. "In the future, it could be interesting to investigate whether transcriptional regulation of CiC and CACT is relevant in diseases associated with insulin signal deregulation, such as obesity and metabolic syndrome." (PMID 27231907, 2016).
Non-alcoholic fatty liver disease (1 paper, 2021). "In agreement with this idea, the activity of CTPI-2 and of a liver-targeted CIC knockout was recently studied in a well-established murine model of diet-induced Non-alcoholic fatty liver disease (NAFLD) and non-alcoholic steatohepatitis (NASH), the diet-induced obesity (DIO) mouse model." (PMID 33499062, 2021).
osteoporosis (1 paper, 2021). A condition of reduced bone mass, with decreased cortical thickness and a decrease in the number and size of the trabeculae of cancellous bone (but normal chemical composition), resulting in increased fracture incidence. "Similar to our observations in murine aged MSCs, CiC levels were decreased in old individuals suffering from osteoporosis, compared with young healthy individuals." (PMID 37117628, 2021).
prostate tumors (1 paper, 2022). "Here, we show that two neighboring transcription factors, Capicua (CIC) and ETS2 repressor factor (ERF), which are co-deleted in human prostate tumors can drive prostate oncogenesis." (PMID 36383412, 2022).
small cell osteosarcoma (1 paper, 2022). "A recent study of small cell osteosarcoma identified 10/36 with a gene fusion involving DUX4 and CIC." (PMID 35887382, 2022).
spinocerebellar ataxia type 1 (1 paper, 2016). Spinocerebellar ataxia type 1 (SCA1) is a subtype of type I autosomal dominant cerebellar ataxia (ADCA type I) characterized by dysarthria, writing difficulties, limb ataxia, and commonly nystagmus and saccadic abnormalities. "A pathological poly-glutamine expansion in ATXN-1, causally related to spinocerebellar ataxia type 1 (SCA1), e.g., was found to induce binding of the protein to RBM17 rather than CiC, thereby promoting disease." (PMID 27200083, 2016).
stomach adenocarcinomas (1 paper, 2017). "CIC encodes a transcriptional repressor, capicua (CIC), whose disrupted activity appears to be involved in several cancer types, including type I low‐grade gliomas (LGGs) and stomach adenocarcinomas (STADs)." (PMID 28295365, 2017).
transitional cell carcinoma (1 paper, 2025). A malignant neoplasm arising from the transitional epithelium, usually affecting the urinary bladder, ureter, or renal pelvis.
tumor (65 papers, 2013 to 2026). "We found that the expression of UGT2B4 was positively associated with expression of multiple well-known oncogenes such as SPINK1, IDH1, MYC, and SRC and negatively associated with expression of well-known tumor suppressors such as CIC and ERF." (PMID 33391440, 2021). "Conversely, R215 and R1512/R1515 mutations in CIC are described to be LOF; however, CIC is a known tumor suppressor that upon disruption leads to enhanced MAPK signaling." (PMID 33106165, 2020). "The transcriptional repressor Capicua (CIC) has been identified as a likely tumor suppressor, as CIC mutations and/or reduced expression are found in several cancers." (PMID 31043608, 2019). "Similar to the analysis comparing primary and recurrent tumors, the mutation status differed among tumor regions, even that of major driver genes such as CIC, FUBP1, PTEN, and NOTCH1." (PMID 28270234, 2017). "CIC mutations were identified in all 4 tumor regions with high methionine uptake or enhancement, while no CIC mutation was found in regions with low methionine uptake or no Gd enhancement." (PMID 28270234, 2017). "Exome sequencing confirmed the IDH1 mutation and revealed novel mutations in FUBP1 and CIC in the primary tumor as well as the xenograft relative to the normal patient genome." (PMID 23527265, 2013). "However, other rare oncogenic fusions such as MN1, PATZ1, BCOR and CIC do appear to be diagnostic for specific tumor types." (PMID 39409964, 2024). "Notably, our results also explain distinct patterns of human CIC mutations that either inactivate CIC tumor suppressor function or produce oncogenic fusions between CIC and the DUX4 activator factor." (PMID 28278156, 2017). "Additionally, the IDH1/IDH2 mutations characteristic of ODG tumours where CIC mutations are found result in the overproduction of 2‐hydroxyglutarate (2‐HG), which has the downstream consequence of widespread hypermethylation of CpG sites and histone tail residues." (PMID 34767259, 2022). "Multiple distinct CIC mutations have also been found within different regions of single lesions 1, indicating that multiple, independently arising CIC mutations may contribute to the progression of a single tumour." (PMID 28295365, 2017). "Tumor samples were examined histologically, and RNA sequencing was performed to confirm the presence of the CIC::DUX4 fusion." (PMID 41053525, 2025). "The loss of two bona fide MAPK pathway tumor suppressors conferred resistance to VT107: NF1, which functions in the upstream part of the signal transduction pathway; and CIC, a transcription repressor." (PMID 39103676, 2024). "Apart from its role in tumor cell invasion, Capicua (CIC), a member of the High Mobility Group-box (HMG-box) transcriptional repressor superfamily, is significantly correlated with its target gene AGRN." (PMID 39691475, 2024). "The mutations were detected both in tumor tissue and CSF samples, apart from FLT4 and CIC mutations." (PMID 37822669, 2023). "DNA and/or RNA sequencing revealed recurrent fusions involving the capicua transcriptional repressor (CIC) gene in 10/10 tumor samples analyzed, with the most common fusion being CIC::LEUTX (n = 9)." (PMID 36964296, 2023). "Activation of receptor tyrosine kinase signaling inactivates capicua (CIC), a transcriptional repressor that functions as a tumor suppressor, via degradation and/or cytoplasmic translocation." (PMID 36619173, 2022). "Increased levels of CiC have been found in human cancers, while inhibition of CiC activity showed anti-tumor activity, and SLC25A1 gene has been implied in epigenetic regulation or cancer biology." (PMID 27231907, 2016).
tumor (continued). "In agreement with our in vitro findings, tumours with wild type CIC (n=5) showed elevated levels of either ACLY or pACLY compared to tumours with mutant CIC proteins (n=5)." (PMID 25277207, 2014). "Strikingly, a tumour sample with a truncated CIC protein (P79X) showed dramatic reductions in ACLY and pACLY." (PMID 25277207, 2014). "Preclinical studies identified CIC::DUX4 to molecularly depend on cell cycle mediators CCNE1 and WEE1 with CCNE1 being established as a direct transcriptional target of CIC::DUX4 that drives tumor growth and survival through an acquired dependence on CCNE/CDK2 complex." (PMID 38882060, 2024). "CIC encodes a transcriptional repressor and MAPK signalling effector that is inactivated by loss-of-function mutations in several cancer types, consistent with a role as a tumour suppressor." (PMID 37345142, 2023). "Our analysis illuminated a tumor evolutionary series of events, which included 1p/19q codeletion, IDH1 R132H, and TERT C250T as early events, followed by loss of function of NDST4 and mutations in FUBP1 and CIC as late events." (PMID 31217899, 2019). "Combining our knowledge of Cic with what was previously known about CIC in tumor development, we propose that CIC is the unknown factor that regulates ETS transcription factors in Ras/MAKP-activated human tumors." (PMID 26683696, 2015). "It is possible that this combination of FUBP1 and CIC mutations, in the absence of other known major gene mutations, gave this particular tumor some kind of growth advantage upon intracranial implantation." (PMID 23527265, 2013). "CIC, which has now been established as a potent tumor suppressor gene, has also been identified as a positive regulator of viral replication which may suggest that the CIC-ATXN1L-TRIM25 axis may be relevant in several different cellular and pathological contexts." (PMID 33115448, 2020). "Thus, FUBP1 and CIC variants appeared to occur secondary to the losses of 1p and 19q during tumor progression and were not necessary changes for tumor initiation in this case." (PMID 31217899, 2019). "Factors such as tumor location (supratentorial vs. infratentorial), age at diagnosis, and the presence of molecular markers (e.g., FOXR2, BCOR, CIC, MN1 alterations) are important for differential diagnosis but are not definitive in isolation." (PMID 40647489, 2025). "This means that the percentage of positive cells is below the cutoff of 15% (10–12% for EWSR1) or that 0% positive tumor cells were detected (for FUS, CIC, and BCOR)." (PMID 36232302, 2022). "The frequency of mutations identified at a higher frequency in our study (IDH1, CIC and FUBP1) are similar to those reported by others for this tumor type." (PMID 25694352, 2015). "Tumor specimens negative for EWS-specific fusion gene should be analyzed for the panel of known fusion transcripts including CIC-rearrangement, BCOR-rearrangement, EWSR1, or FUS fusion with no-ETS partner." (PMID 36358827, 2022). "Conversely, CIC knockdown (KO), pharmacological inhibition using benzenetricarboxylate (BTA) or citrate transport protein inhibitors (CTPI-1/2), or the expression of non-functional CIC mutants significantly reduce cell proliferation, colony formation, and tumor spheroid growth." (PMID 39795950, 2024). "Thus, the presence of an intact CIC gene in other tumor types does not necessarily mean that the CIC protein is a functional repressor." (PMID 30737375, 2019). "The spatial/temporal distribution of FUBP1/CIC mutations may be heterogeneous, whereas the 1p/19q codeletion is homogeneously found within the tumor tissue, and a considerable number of 1p/19q codeleted tumors have no mutations to FUBP1/CIC." (PMID 27503138, 2016).
tumor (continued). "Interestingly, the primary tumor or xenografts did not expand in vitro, even though 1p/19q co-deletion with underlying mutations in both FUBP1 and CIC was present, as revealed by aCGH and exome sequencing." (PMID 23527265, 2013). "Additionally, none of the putative tumor-suppressor genes relevant to LGG, namely, ATRX, CIC, FUBP1, and NOTCH1, showed correlations with overall survival (data not shown)." (PMID 27852048, 2017).